CD4 (CD4 molecule)
Diseases named in the same sentence as CD4 in open-access papers (continued):
Sharing a sentence is not in itself a finding about the gene and the disease.
COVID-19 (continued). "Furthermore, expression levels of genes controlling cell proliferation and apoptosis, such as TGFB1, CDK4, TNFSF10, and TNFRSF10A, were also found to be dysregulated in CD4+ T cells of patients who recovered from COVID-19." (PMID 34784300, 2021). "As many studies have shown a higher viral load in more severe COVID-19 cases, the increase in CD4+ T cells in those with a severe outcome, might be only a result of the increased antigenic burden." (PMID 34223911, 2021). "Thus, several studies have demonstrated that patients with severe COVID-19, when compared to patients with mild COVID-19, exhibit less robust CD4+ and CD8+ T cell responses against SARS-CoV-2 membrane, nucleocapsid, and spike proteins." (PMID 33841434, 2021). "Nevertheless, COVID-19 patients show clearly elevated frequencies of CD4+ memory T cells." (PMID 34228322, 2021). "Whereas the frequency of CD4+ T cells is significantly lower in patients with COVID-19 compared to healthy controls, a recent study identified some functional signals of Th2 cells, such as the degranulation of basophils and eosinophils in hospitalized patients." (PMID 35126355, 2021). "CD4+ T cell differentiation and functional profiles in critically infected patients with COVID-19." (PMID 34283810, 2021). "For RBD mRNA-LNP, it has also been demonstrated that a single immunization elicited potent CD4+ and CD8+ T cell responses in lungs in addition to spleens, indicating a potential contribution to immune protection against SARS-CoV-2 infection." (PMID 33536425, 2021). "Collectively, these data demonstrate impairment of Ag-specific CD4+ T cells in fatal COVID-19, and suggest that CD4+ T cells may have a protective role in this setting." (PMID 34529726, 2021). "If the presence and rapid deployment of highly functional SARS-CoV-2-specific CD8 and CD4 T cells is linked with control and mild/absent disease, several open questions concerning the role of virus-specific T cells during severe COVID-19 remain unsettled." (PMID 34471260, 2021). "Here we have described the clinical features of COVID-19 from the perspective of the patient’s cellular immunity status and found that patients with reduced baseline CD4+ T cell counts were more likely to be older, have higher levels of LDH, more severe symptoms, and have hypertension." (PMID 34149679, 2021). "On the other hand, it is noteworthy that suppression of the effector CD4 T lymphocyte could be beneficial for mitigating the progress of COVID-19." (PMID 34646783, 2021). "Flow cytometric analysis of peripheral blood mononuclear cells from patients with advanced COVID-19 showed a significant rise in activated CD4+ T cells and CD14+HLA-DRlo inflammatory monocytes known to produce granulocyte-macrophage colony-stimulating factor (GM-CSF)." (PMID 34603758, 2021). "In terms of the association between MD and disease severity, it is possible that MD-related poor responses of CD4 TEM and memory CD8 T cells might be linked with COVID-19 disease progression or severity." (PMID 35095881, 2021). "Lymphopenia in severe COVID-19 patients is met with decreases in both CD4+ and CD8+ T cells." (PMID 34326843, 2021). "Also, generalized lymphopenia was observed in active COVID-19 relative to convalescent phase, particularly in various CD4+ and CD8+ T cell, NKT, MAIT cell and certain B cell immunotypes." (PMID 34867943, 2021). "However, PD-1 expression and the memory maturation profile of SARS-CoV-2–specific CD4+ T cells were comparable between COVID-19 patients stratified by their WHO score." (PMID 33945513, 2021). "Additionally, ex vivo studies with COVID-19 patients showed that reactive CD4+ T cells are able to produce high levels of chemokines." (PMID 34571855, 2021). "Similarly, it has been reported that in COVID-19 patients the CD4 T cell responses to S are the most abundantly detected responses, followed by the responses to N and M.Corresponding mechanisms should be addressed in future studies." (PMID 35003131, 2021).
COVID-19 (continued). "Whether high magnitude of cross-reactive CD4+ T cells are contributing to this less severe outcome needs to be addressed in the prospective cohort before and after COVID-19." (PMID 33777028, 2021). "A lower number of CD4+ may predict a longer duration of viral RNA in the stools of patients with COVID-19." (PMID 33669527, 2021). "Strong CD4+ T-cell reactivity to the viral S, Membrane (M), and Nucleocapsid (N) proteins was observed in mild COVID-19 immunocompetent patients, but M protein induced the highest frequencies of CD4+ T cells, when compared to S and N proteins, in severe COVID-19 patients." (PMID 34835067, 2021). "Furthermore, the S2 protein of the 229E/OC43 coronaviruses has been found to be cross-reactive with CD4+ T cells of COVID-19 infected individuals." (PMID 34681059, 2021). "Additionally, several studies reported the detection of SARS-CoV-2-specific CD8+ and CD4+ T cells in the majority of COVID-19 convalescent patients approximately 3–5 weeks PSO7,21–23." (PMID 33563974, 2021). "Thus, COVID-19 patients were characterized by expanded populations of activated, PD-1 and perforin expressing CD4 T cells in a subgroup of patients." (PMID 33777054, 2021). "However, COVID-19-recovered older participants (n = 51) had greater antibody and T-cell responses, including IFNγ+ and IFNγ+IL-2+TNFα+-specific CD4+ T cells (p < 0.0001), as well as TNFα+-specific CD8+ T cells (p < 0.001), than COVID-19-naive older adults." (PMID 34868051, 2021). "Overall, our results showed that the functional and phenotypical signature of SARS-CoV-2–specific CD4+ T cells, rather than magnitude, was associated with COVID-19 severity in hospitalized patients." (PMID 33945513, 2021). "Lymphopenia is a common finding in COVID-19, affecting both CD4+ T cells and CD8+ T cells, more significantly in critically ill patients, considering that T cell response may be either diminished or overactivated." (PMID 34829920, 2021). "In terms of computed tomography findings, the moderate COVID-19 patients in the lower CD4+T cell level group more often represented as patchy local shadowing (45 [47.4%] vs. 33 [32.4%], P=0.031) compared with the moderate COVID-19 patients in the higher CD4+T cell level group." (PMID 33435865, 2021). "Larger studies that include more robust data on CD4 counts and viral loads might provide a more nuanced picture of the potential impact of HIV disease status on COVID-19–associated morbidity and mortality." (PMID 34081684, 2021). "We, therefore, speculate the purine pathways of recovered COVID-19 patients may be related to the role of CD4+ T cells." (PMID 34021116, 2021). "According to them, the biological role of pre-existing SARS-CoV-2 S-cross-reactive CD4+ cells remains unclear for now but they might represent the key to understanding vast divergent manifestations of COVID-19." (PMID 33937545, 2021). "In particular, the level of a type of sphingolipids (i.e., monosialodihexosyl gangliosides, GM3s) in the plasma was negatively correlated with CD4+ T-cell count in COVID-19 patients, and accordingly, the plasma from severe patients contained GM3-enriched exosomes." (PMID 34737743, 2021). "Several studies suggested a potential role of CD4+ T cells in COVID-19 severe respiratory syndrome." (PMID 34335703, 2021). "Recently, it has been reported that SARS-CoV-2 virus-specific T-cells were detected in the majority of COVID-19 patients, specifically the circulating SARS-CoV-2-specific CD8+ and CD4+ T cells in about 70% and 100% of COVID-19 convalescent patients, respectively." (PMID 33918624, 2021). "Here, we used flow cytometry to assess the magnitude, function, and phenotype of SARS coronavirus 2–specific (SARS-CoV-2–specific) CD4+ T cells in 95 hospitalized COVID-19 patients, 38 of them being HIV-1 and/or tuberculosis (TB) coinfected, and 38 non–COVID-19 patients." (PMID 33945513, 2021).
COVID-19 (continued). "Taken together, these results also suggest that CD4+ T cells from COVID-19 could be key players on inflammatory and antiviral responses upon a second exposition, which would be advantageous for the vaccines." (PMID 34571855, 2021). "Likewise, in a study by Braun and colleagues that involved 68 SARS-CoV-2-unexposed healthy donors and 25 PCR-confirmed COVID-19 patients, the authors also identified S glycoprotein-reactive CD4+ T cells in 35% of the healthy participants." (PMID 33672450, 2021). "Furthermore, patients with COVID-19 show increased Fas and PD-1 expressions in both CD4+ and CD8+ T cells." (PMID 34163490, 2021). "Interestingly, the portion of CD3+CD4+ T cells expressing α4β7 was substantially reduced in previous COVID-19 patients compared to healthy controls." (PMID 33959123, 2021). "Both analyses showed that based on the functional and phenotypical traits of SARS-CoV-2–responding CD4+ T cells, COVID-19 patients could be distinguished from non–COVID-19 controls." (PMID 33945513, 2021). "On the contrary, high levels of neutralizing antibodies were associated with severe disease and ICU visits in many COVID-19 patients suggesting an imbalanced CD4 T-cell response is not optimal for protection." (PMID 34162945, 2021). "Moreover, as COVID-19 patients are under immunosuppressive conditions, particularly T CD4+ and CD8+ lymphocytopenia, this provides an encouraging background for the occurrence of persistent fungal co-infections." (PMID 34575758, 2021). "Interestingly, SARS-CoV-2 spike-reactive CD4+ T cells, which focus on C-terminal S epitopes, can be detected both in patients with COVID-19 and in healthy donors." (PMID 34917088, 2021). "Five RCTs reported CD4+ in COVID-19 patients treated with CHM." (PMID 35127733, 2021). "Considering the presence of memory T cell responses against structural proteins of SARS-CoV after 9 and 11 years of recovery, long-term protection against COVID-19 depends upon the presence of antigen-specific memory T cell response against SARS-CoV-2 which is predominated by CD4+ T cells." (PMID 35250966, 2021). "Moreover, CD4+ T lymphocyte count < 400 cells/mm3 was observed in 24% of the COVID-19 group and 5% of the post-COVID group." (PMID 34635073, 2021). "Thus, in the current study, we carried out scATAC-seq and scRNA-seq using PBMCs and emphatically depicted the chromatin landscape and transcriptomic immune profiling of patients with COVID-19 in T cells, CD4+T cells, and CD8+ T cells." (PMID 33717140, 2021). "CD4+ T-cells from 1–3 months post-symptom onset of COVID-19 may be primed to respond quicker and more strongly to activation signals." (PMID 34835045, 2021). "Similarly, in the severe patients (59 CAP and 39 COVID-19), COVID-19 patients had increased CD3+CD4+% and decreased CD3+CD8+%, compared with that of CAP patients." (PMID 34150910, 2021). "However, CTSL tended to be comparable in CD4 + T cells from COVID-19 pneumonia patients, suggesting the particularity of CTSL in T cells infected with the virus that causes COVID-19." (PMID 34497809, 2021). "Moreover, in these patients, the memory maturation profile and expression of other activation markers (such as CD38, Ki67, and PD-1) in M. tuberculosis–specific CD4+ T cells were similar between COVID-19 patients and hospitalized non–COVID-19 controls." (PMID 33945513, 2021). "In adult COVID-19, PD-1 expression by CD4+ T cells was elevated." (PMID 33653907, 2021). "Furthermore, the expression of activation and/or exhaustion markers by CD4+ T cells, have been observed in patients with severe COVID-19 symptoms." (PMID 35126355, 2021). "Patients on antiretrovirals and with CD4 cell counts higher than 200/μL might have a mild or moderate course of COVID-19, should ARVs have an effect on SARS-CoV-2." (PMID 32574323, 2020). "Moreover, COVID-19 patients had lower level of regulatory T cells (CD3+CD4+CD25+CD127low+), especially in severe cases." (PMID 32695683, 2020).
COVID-19 (continued). "It is reported that CD4+ T cell count was lower in severe COVID-19 patients." (PMID 33336061, 2020). "However, SARS-CoV-2-specific CD4+ T cells were detected in only 77% of acute COVID-19 samples (23/30), with similar observations for individual peptide pools (S, M, N, and MP_R)." (PMID 33010815, 2020). "Furthermore, IL2RA was significantly upregulated in CD4+ T-cells from severe COVID-19 patients compared to moderately affected patients." (PMID 33178221, 2020). "In addition, this study indicated that low CD4+ levels and high levels of viral load influence the lethal progression of COVID-19." (PMID 32815513, 2020). "Interestingly, post COVID-19 patients had significantly higher frequencies of tp SARS-CoV-2 NCAP-reactive CD4+ T cells clearly distinguishing them from unexposed HC (p=0.0043)." (PMID 33424856, 2020). "By in silico sorting CD4+ T-cells from a single cell RNA-seq dataset, we found that CD4+ T-cells were highly activated and showed unique differentiation pathways in the lung of severe COVID-19 patients." (PMID 33178221, 2020). "Lymphopenia, particularly in CD4+ and CD8+ T-cells, as well as reduced interferon (IFN)-γ production by CD4+ T-cells but not CD8+ T cells or natural killer cells are associated with the increased severity of COVID-19." (PMID 32570850, 2020). "This is because as it is with SARS-CoV infection, the acute phase of COVID-19 is characterized by a remarkable reduction in CD4 T cell population and this could be prolonged reaching a lowest point at days 7-9 before returning to normal." (PMID 32952832, 2020). "Additionally, the difference in CD4+ cells median proportion between COVID-19 X-ray (−) and COVID-19 X-ray (+) was observed (respectively, 23.1% vs. 8.0%, p = 0.0026)." (PMID 33291439, 2020). "It has recently found that AZD1222 could induce a robust humoral, CD8 and Th1 dominant CD4 response in mice and rhesus macaques and that both a prime and a prime-boost regimen protected rhesus macaques against COVID-19 related pneumonia." (PMID 33101309, 2020). "Furthermore, several studies observed a TH1 signature of CD4 T cells in COVID-19 patients, although in one study TH17 signatures were reported." (PMID 33262067, 2020). "In addition, relative increased recirculation of activated CXCR5+PD-1high CD4+ Tfh cells is observed in severe COVID-19." (PMID 33384690, 2020). "The frequency of activated CD4+ cTfh cells was also increased in a large proportion of donors with severe COVID-19 but did not associate with plasmablast frequency." (PMID 32669287, 2020). "In the late stage of COVID-19, severe cases had extremely low CD4+ T cells and CD8+ T cells, but unusually high neutrophils [6.5 × 109/L (IQR, 4.8–9.6)], procalcitonin [0.27 ng/mL (IQR, 0.14–1.94)], C-reactive protein [66 mg/L (IQR, 25–114)] and an extremely high level of interleukin-6." (PMID 32983157, 2020). "Looking at the activation as measured by HLA-DR and CD38 expression, we observed an increase of HLA-DR+CD38+ cells in the TM and EM subset of CD8+ T cells and in the CM and TM subset of CD4+ T cells in both COVID-19 and malaria patients compared to healthy controls." (PMID 32983106, 2020). "Indeed, 100% of recovered COVID-19 patients in a recent study had virus-specific CD4+ T cells, which is highly suggestive of a critical role of adaptive immunity in successful clearance of SARS-CoV-2." (PMID 32556942, 2020). "In addition, flow cytometric analysis of a blood sample from this COVID-19 patient revealed that CD4 and CD8 T-cells were hyperactivated and proinflammatory CCR4+ CCR6+ Th17 in CD4 T-cells markedly increased." (PMID 34676126, 2020). "This upregulation of HLA-DR/CD38 on T cells co-expressing PD1 and LAG-3 and PD1 and TIM-3 could be observed on both CD8+ and CD4+ T cells in COVID-19 and malaria patients." (PMID 32983106, 2020). "We found reduced CD4+ Tregs in COVID-19 patients and an increased ratio of Th17/Tregs." (PMID 33375675, 2020).
COVID-19 (continued). "Additionally, the proportion of CD8+ T cells producing TNF-α was significantly higher in COVID-19 patients compared to healthy controls (p = 0.0214), and a similar tendency was observed for CD4+ T cells." (PMID 32707842, 2020). "Indeed, the first COVID-19 post-mortem study reported extensive alveolar edema with macrophages and monocyte infiltrations of the lung and a decrease in CD4+ and CD8+ cells and an increase in Th-17 cells, which were related to high IL-6 levels." (PMID 33382773, 2020). "Similarly, severe cases of COVID-19 are accompanied by a reduction in all lymphocyte populations: B, CD4+ T, CD8+ T, and NK cells, and by neutrophilia." (PMID 33584667, 2020). "Severe COVID-19 is histologically characterized by diffuse alveolar damage with hyaline membranes, edema, fibrin deposits, multinucleated cells, type II pneumocyte hyperplasia and lymphocyte infiltration composed of a mixture of CD4 and CD8 lymphocytes." (PMID 32803199, 2020). "Broadly directed, antigen-specific T cell responses could be detected in the effector and central memory subsets of CD8+ and CD4+ T cells of COVID-19 patients." (PMID 32983106, 2020). "T cell responses in post COVID-19 HC could be distinguished from unexposed HC by higher frequencies of triple-positive NCAP reactive CD4+ T cells." (PMID 33424856, 2020). "Additionally, sepsis-induced immuno-paralysis is characterized by lymphopenia, mainly through CD4+ T-lymphocytes, which makes it possible to consider severe COVID-19 intoxication as a sepsis-like syndrome or viral sepsis." (PMID 32722596, 2020). "However, T cell and CD4+ T cell subset population significantly increased at week 4 in patients with severe COVID-19." (PMID 33261583, 2020). "We proposed that effector T CD8+ cells and memory T CD4+ cell response together with plasmablasts provided a reliable measurement of immune status that may be useful for evaluating COVID-19 patients." (PMID 33291439, 2020). "Furthermore, absence of these virus-specific cells leads to uncoordinated antigen-specific immune responses and failure to control COVID-19, predominantly in older individuals with low naïve CD4+ T cells." (PMID 33384690, 2020). "We addressed these questions in a comprehensive study of three well-characterized groups of COVID-19 patients with different disease outcomes (moderate, severe, deceased) by quantifying virus loads, Ab responses as well as CD4 T cell responses over the entire time of hospitalization." (PMID 33262993, 2020). "Patients recovered from COVID-19 have substantial CD4+ and CD8+ T cell responses to SARS-CoV-2." (PMID 33362793, 2020). "Leukocyte, neutrophil, lymphocyte, CD3+ and CD4+ count at admission could predict the mortality due to COVID-19." (PMID 33125396, 2020). "Our results suggest that the decrease in the number of CD4+ T lymphocytes in patients with COVID-19 may be related to the excessive consumption of CD4+ T lymphocytes." (PMID 32976531, 2020). "However, a recent study identified circulating SARS-CoV-2-specific CD8+ and CD4+ T cells in ~70% and 100% of recovered COVID-19 patients, respectively." (PMID 32695122, 2020). "Finally, a study of 69 COVID-19 patients found that CD4 expression on monocytes was decreased in the 16 patients with severe COVID-19." (PMID 33375371, 2020). "Altogether, our data indicate concomitant response of CD8+ and CD4+ T cells in the adaptive immune system of the COVID-19 patients, and the clonally expanded CD8+ effector cells in the patients may ultimately develop into long-lived memory T cells." (PMID 32796814, 2020). "In severe COVID-19 cases, the macrophage-epithelial interaction promotes a further augmentation of IL-6 (and IL-2R, IL-10, and TNFα), whereas CD4+ (including IFNγ-expressing CD4+ T cells) and CD8+ T-cells markedly decrease in number." (PMID 32517353, 2020).